IL9 (interleukin 9)
Diseases named in the same sentence as IL9 in open-access papers (continued):
Sharing a sentence is not in itself a finding about the gene and the disease.
tumor (continued). "Th9 cells and their primary cytokine, IL-9, can exhibit either pro-tumor or anti-tumor activity depending on the type of tumour and the surrounding microenvironment." (PMID 39325360, 2025). "For instance, tumors that are IL-9 high have 2.1-fold greater densities of CTL in contact with tumor cells than IL-9 low tumors." (PMID 40497965, 2025). "To learn more about how much cytokine and chemokine levels varied in different tumor compartments depending on the T cell infiltration, we grouped the data of the top four proteins, IL-9, CXCL10, CCL4, and VEGF, median-based into high and low." (PMID 40497965, 2025). "Preclinical studies have highlighted the synergistic anti‐tumour effects of combining p66Shc inhibitors with anti‐IL‐9 monoclonal antibodies, disrupting tumour‐supportive microenvironments." (PMID 40690563, 2025). "In good agreement with our data, it has been described that IL-9 can be produced by CD8+ T cells and that IL-9-producing CD8+ T cells convey an enhanced anti-tumor immunity." (PMID 40497965, 2025). "IL-9 has both tumorigenic and antitumorigenic properties depending on the type of cancer and the tumor microenvironment." (PMID 38825637, 2024). "Th9 cells are known to elicit strong host antitumor CD8+ cytotoxic T lymphocyte (CTL) responses by promoting Ccl20/Ccr6-dependent recruitment of dendritic cells to tumor tissues via IL-9 production." (PMID 39187636, 2024). "To further investigate the link between Th9 cells and ACC1-mediated fatty acid biosynthesis in the context of cancer, we next treated tumor-inoculated mice with IL-9–neutralizing antibodies (αIL-9)." (PMID 39187636, 2024). "Our results demonstrate that IL-9 secreted by leukemic cells negatively modulates the anti-tumor immune abilities of CTLs, highlighting a new suppressive mechanism and a novel potential therapeutical target in CLL." (PMID 38360867, 2024). "Within the combination treatment groups of anti-PD-1 and carbo/pax, the cytokines positively correlating with tumor burden were G-CSF (0.84700, p = 0.0334), IL-9 (r = 0.8174, p = 0.0470), and CXCL9, also known as MIG (r = 0.9072, p = 0.0125)." (PMID 39623404, 2024). "In mouse melanoma and myeloma subcutaneous tumor models, the immunization of mice with Dectin-1-activated DCs induced potential Th9 and IL-9-dependent anti-tumor immune responses." (PMID 39590166, 2024). "IL-9 can significantly promote the proliferation of tumour cells and prevent IFN-γ-induced tumour cell apoptosis by activating the signal transducer and activator in the transcription 3 (STAT3) signal pathway." (PMID 38475858, 2024). "In summary, our current study demonstrates that vvDD-IL-9 treatment can deliver IL-9 into the tumor bed and elevate IL-10 expression." (PMID 38473379, 2024). "Together, these studies suggest that noncoding cis-REs modulate IL-9 expression, thereby affecting homeostatic tumor surveillance." (PMID 38825637, 2024). "In this study, IL-9 was delivered into tumor beds via vvDD and strong antitumor effects have been demonstrated in two non/low immunogenic tumor models." (PMID 38473379, 2024). "SATB1, a global chromatin organizer, is dysregulated in human cutaneous TCL by promoting the expression of TH-2 cytokines (IL-5 and IL-9), which were appropriate for the tumor microenvironment." (PMID 39176397, 2024). "IL-9 always plays an antitumor function in most solid tumors while it promotes tumor progression in hematological neoplasms and in some solid tumors." (PMID 38473379, 2024). "Both IL-9 and IL-4 are components of the tumor’s immunosuppressive microenvironment, aiding cancer cells in evading immune responses." (PMID 39727942, 2024). "In the majority of solid tumors IL-9 acts as an anti-tumoral factor by promoting tumor cell apoptosis and activating innate and adaptive anti-tumoral immune responses." (PMID 39281678, 2024).
tumor (continued). "Consistent with our in vitro experiments, mice that received TOFA-treated cells, which presented increased IL-9 expression, presented significant tumor regression compared with that of mice that received untreated Th9 cells." (PMID 39187636, 2024). "In the context of GM-BMDC-based tumor immunotherapy, IL-33 administration reportedly drives the induction of IL-9-producing CD8+ T cells, potentiating the inhibition of tumor growth." (PMID 38825642, 2024). "Very limited information is available concerning the ability of IL-9 to interfere with the anti-tumor functions of T cells." (PMID 39281678, 2024). "Blockade of IL-9 diminishes the tumor growth-inhibiting effects, indicating that IL-9, modulated by RORγ, plays a critical role in tumor suppression." (PMID 39518891, 2024). "IL-9, produced by activated T cells, is known to inhibit tumor cell proliferation and promote cytotoxicity in solid tumors." (PMID 39623404, 2024). "In summary, plasma IL-9, tumor IL-8 gene signature levels, and tumor stroma-rich subtype represent potential biomarkers of response to NAC-ICI." (PMID 38789460, 2024). "Here, we used the oncolytic vaccinia virus (oVV) to deliver interleukin-9 (IL-9) into the tumor bed and explored its antitumor effects in colon and lung tumor models." (PMID 38473379, 2024). "Nevertheless, given their overarching effects on tumour immunity, acting upstream of the main effector type 2 cytokines IL-4, IL-5, IL-9, and IL-13 and T cells, the prospect of therapeutically targeting these cytokines is promising." (PMID 37455828, 2023). "A study on mouse melanoma examined the mechanism by which adoptive cell transfer with IL9+CD8+ cytotoxic T cells (Tc9) elicits a stronger anti-tumor response than with classical ones (Tc1)." (PMID 37833991, 2023). "Second, the intratumoral combination of TAMs and IL9 significantly increased the total number of tumor-infiltrated immune cells, which included DCs, CD103+ DCs, macrophages, NKs, T cells, and especially cytotoxic effector T cells." (PMID 36968220, 2023). "The resident macrophages at the newly developing tumor site were polarized toward the M1-like phenotype by IL9." (PMID 36968220, 2023). "When analyzing tumor samples from 20 patients with colorectal cancer, the authors found that IL-9+ TILs expressed higher levels of PD-1 than other populations of TILs." (PMID 37189417, 2023). "IL-9 secreting Th9 cells play a role in various immune processes such as allergic responses, tumor suppression, immunity against pathogens, and immune-mediated diseases." (PMID 37386045, 2023). "Further research is required to examine the contribution of different IL-9-producing immune cell types in the TME rescued by PD-1 blockade to the observed anti-tumor response." (PMID 37189417, 2023). "IL-9 promotes tumor progression in hematological tumors through its lymphocyte growth factor activity." (PMID 36154925, 2023). "Collectively, our results proved that the presence of TAMs at the early timepoint of tumor progression is important for the antitumor effect of IL9." (PMID 36968220, 2023). "IL-9 and IL-9-secreting cells serve as double-edged swords in tumor immunity with both pro-tumorigenic and anti-tumorigenic role in cancer development." (PMID 36154925, 2023). "IL-9 can also act directly on tumor cells expressing IL-9R, such as squamous cancer (SqC) cells and cervical cancer, to directly kill these tumor cells." (PMID 36936961, 2023). "In contrast, IL-9 always plays an anti-tumor function in solid tumors via activating innate and adaptive immune responses." (PMID 36154925, 2023). "Taken together, the combination of IL9 and macrophages induced the accumulation of immune cells in the tumor, probably by producing chemotactic chemokines." (PMID 36968220, 2023).
tumor (continued). "The absence of macrophages at the initial time, as in the case of the B16F10-IL9–only group, or the partial depletion of TAMs during tumor progression, as in the case of treatment with clodronate, abolished the antitumor effect of IL9." (PMID 36968220, 2023). "IL-9 has opposing effects on IL-9R-positive tumor cells: from cytostatic and cytotoxic effects to promoting tumor cell growth and migration." (PMID 37189417, 2023). "It is worth noting that IL-9 has been shown to activate adaptive immune to suppressive tumor growth in various tumors, but it has a tumor-promoting effect in T cell-derived hematological cancers." (PMID 38288118, 2023). "Vice versa, Tc9 cells had lower cholesterol levels than Tc1 cells and, hence, elevated IL9, which fosters Tc9 cell persistence and anti-tumor efficacy." (PMID 37833991, 2023). "To generate a consistent expression of IL9 in the tumor microenvironment (TME), we used a stable B16F10 cell line secreting IL9, called B16F10-IL9." (PMID 36968220, 2023). "The microscopic analysis of H&E stains of tumor tissues provided evidence of immune cell infiltration into tumor tissues in the presence of IL9." (PMID 36968220, 2023). "High expression of IL9 in tumor tissues was related to prolonged survival of patients with colon carcinoma." (PMID 36968220, 2023). "Although its role in cancer is still unclear, current researches suggest that the IL-9 shows anticancer effects by controlling the T cell function and removing the tumor cells in CRC microenvironment." (PMID 37612430, 2023). "First, intratumoral IL9 shifted the resident macrophages at the newly developing tumor site to the M1 phenotype, thus, minimizing the protumor effects of general TAMs." (PMID 36968220, 2023). "In contrast, IL9 can inhibit tumor progression directly by inhibiting the proliferation and migration of cancer cells or indirectly by activating innate and adaptive immunity to trigger antitumor responses." (PMID 36968220, 2023). "Human TH9 cells also promoted the cytotoxic function of CD8 T cells against autologous tumor cells in an IL-9- and IL-21-dependent manner." (PMID 37189417, 2023). "Th2 cells are a crucial component of type II immune responses by secreting a wide spectrum of cytokines such as IL-4, IL-5, IL-9 and IL-13, which affect both tumor cells and several types of immune cells." (PMID 36376448, 2023). "At first, the presence of IL9 within the tumor area was essential to generating proper antitumor immunity." (PMID 36968220, 2023). "The study revealed that IL-9 stimulation increased MHC I expression in tumor cells in an ERK-dependent manner, which promoted tumor infiltration with T cells." (PMID 37189417, 2023). "ELISA measurements in B7H4 staining positive tumours: IL-9, IL-18, IP-10(CXCL10), MIG (CXCL9) and SDF-1a (CXCL12)." (PMID 36980202, 2023). "For this purpose, an IL9-secreting tumor cell line that evenly and continuously distribute IL9 throughout the tumor mass, was used for syngeneic implantation." (PMID 36968220, 2023). "We will also discuss the role of host factors like the microbiota and TGFβ in the tumor microenvironment (TME) in the regulation of IL-9 secretion and anti-PD-1 treatment efficacy." (PMID 37189417, 2023). "We specifically showed that IL9-polarized TAMs induced antitumor immunity in mice by recruiting antitumor immune cells into the tumor mass via releasing the macrophage-derived chemoattractants, CCL3/4 and CXCL9/10." (PMID 36968220, 2023). "Such antitumoral response is mediated by IL-9 secreted by Th9 cells and involves the recruitment and survival of dendritic cells to the tumor site." (PMID 36980536, 2023). "IL-9 can synergize with PD-1 blockade in eliciting an anti-tumor immune response as demonstrated by recent findings." (PMID 37189417, 2023).
tumor (continued). "Together with the known role of IL-9 in CD8 T cells in cancer, these studies suggest that IL-9 responses rescued by anti-PD-1 treatment contribute to the effect of anti-PD-1 therapy by promoting anti-tumor CD8 responses." (PMID 37189417, 2023). "The authors found out that, due to iNOS activity, the classic Th2 response was completely (IL‐4 and IL-13) or markedly (IL‐5, IL‐6, IL‐9, and IL-10) inhibited after tumor irradiation." (PMID 37347290, 2023). "For example, Th9 cells produce IL-9 in solid tumors and enhance tumor-specific cytotoxic T lymphocyte (CTL) responses in vivo." (PMID 36936961, 2023). "Accordingly, nivolumab treatment suppressed growth and induced apoptosis of tumor cells only in the high IL-9 group." (PMID 37189417, 2023). "The fact that Arg1-expressing macrophages can rescue tumor growth in Il9r−/− mice indicates Arg1 is a critical effector in IL-9-macrophage mediated tumor growth." (PMID 35778404, 2022). "In the case of IL9, we revealed that patients with high stromal IL9 levels (prognostic beneficial) show a significant tumor-to-stroma IL9 gradient towards the stroma." (PMID 36131941, 2022). "Immunofluorescence double staining for CD4 and PU.1 revealed significantly more PU.1+ CD4+ T cells in the lamina propria of tumour patients, suggesting that IL-9 producing cells in CRC and CAC are Th9 cells." (PMID 35793807, 2022). "But the IL-9+ lymphocyte infiltration was found to be related with the differentiation of tumor, survival of patients and expression of progesterone receptor in EC, indicating an association between IL-9 and EC." (PMID 36531027, 2022). "In case of IL9, patients with high stromal expression (favorable prognosis) have their tumor-to-stroma IL9 gradient directed towards the stroma." (PMID 36131941, 2022). "IL-9 alters macrophage subsets in the lung and promotes tumor growth in a macrophage- and Arg1-dependent manner." (PMID 35778404, 2022). "Here, the authors show that IL-9 promotes the expansion of pulmonary macrophages and that targeting the IL-9R/arginase 1 axis restricts tumor growth, thus identifying this cytokine pathway as a potential therapeutic target." (PMID 35778404, 2022). "In subsequent experiments, we performed studies in the syngenic LL/2 model and analyzed the direct anti-tumoral function of IL-9 on the tumor cell line LL/2 by using Ki67 and AnnexinV/PI as proliferation and apoptosis markers, respectively." (PMID 35514957, 2022). "Together with IL-6, IL-9 led to tumour cell proliferation, and the targeting of IL-9 by neutralising antibodies suppressed colorectal tumorigenesis." (PMID 35793807, 2022). "To explore if the regulatory pattern of IL-9 on macrophages is also consistent in other tumor environments, we also assessed IL-9R in a B16 s.c. model." (PMID 35778404, 2022). "One possible explanation for these differences relates to IL-9 target cells in different tumor types." (PMID 35514957, 2022). "In contrast, patients with low stromal IL9 levels showed a tumor-to-stroma IL9 gradient towards the tumor epithelium." (PMID 36131941, 2022). "Mechanistic experiments demonstrated that IL-9 signalling controls IL-6 production by tumour-infiltrating T cells, leading to IL-6-dependent pSTAT3 activation and proliferation of intestinal epithelial cells [IEC]." (PMID 35793807, 2022). "In fact, we noted here that IL-9 controls tumor cell growth in NSCLC via direct effects on IL-9R expressing cancer cells." (PMID 35514957, 2022). "IL-17 derived from myeloid-derived suppressor cells recruits IL-9-producing Treg cells, which in turn secrete the IL-9 involved in the survival of tumor resident mast cells." (PMID 36430483, 2022). "Adoptive transfer of Th9 cells or other IL-9-producing cells limits tumor growth, particularly in models of melanoma." (PMID 35778404, 2022). "In the context of cancer, IL-9 has shown pro-tumor effects on hematological tumors and solid tumors." (PMID 35795670, 2022).
tumor (continued). "IL-9 also changes expression of genes in these populations, including the Arg1 gene that is critical for the pro-tumor activity." (PMID 35778404, 2022). "The recent demonstration of potent anti-tumor activity from T helper 9 (Th9) and other IL-9-producing cells supported these cells as an attractive strategy for cancer cell therapy." (PMID 35778404, 2022). "In this study, we find lung macrophages occupy a large proportion of IL-9-responsive cells in the tumor microenvironment." (PMID 35778404, 2022). "Analysis of effector cytokines Ifng, Il9, Il17a and Il4 mRNA in tumor-infiltrating immune cells revealed that Ifng and Il9, but not Il17a or Il4, expression was increased following cGAMP administration." (PMID 35091453, 2022). "Mice receiving the anti-IL-9 antibody had fewer tumours and a significantly reduced tumour score as compared with controls." (PMID 35793807, 2022). "In conclusion, our findings indicate that IL-9 drives immune escape of lung tumor cells via effects on tumor cell survival and tumor infiltrating T cells." (PMID 35514957, 2022). "In recent years, with the detailed study of IL-9, it has been found that IL-9 can affect normal tissues and cells and exert its functions of anti-tumor and allergic reaction." (PMID 36172190, 2022). "CRC patients showed elevated IL-9 and PU.1 levels in mucosal T cells, indicating an enrichment of Th9 cells in the tumour tissue." (PMID 35793807, 2022). "Tc9 cells resist tumor- or ROS-induced ferroptosis through the IL-9/STAT3/fatty acid oxidation pathway." (PMID 35192544, 2022). "The secretion of IL-9 in tumor microenvironment has been considered as a tolerance factor that inhibits adaptive anti-tumor immunity." (PMID 35211408, 2022). "Conversely, activation of CLEC7A can exert effective anti-tumor immunity by enhancing the expression of interleukin-33 and interleukin-9 in dendritic cells and by inducing differentiation of naive CD4+T cells into T-helper 9 cells." (PMID 35480896, 2022). "IL-9 is increasingly produced by tumor-infiltrating T cells (TILs), as well as tumor cells themselves and a subset of Foxp3 expressing regulatory T cells (Tregs)." (PMID 35681689, 2022). "IL-9 producing Helper T (Th9) cells exert an anti-tumor effect through the secretion of IL-9 and IL-21." (PMID 36078039, 2022). "Interleukin-9 (IL-9) is a cytokine with pleiotropic functions that plays an important role in regulating tumor cell growth." (PMID 35681689, 2022). "Histochemical detection in the tumor tissues revealed differences in the abundance and expression of IL-9, IL-27, and IL-5RA positive cells between probiotic and model groups, and such differences were consistent with changes in the serum cytokine profile." (PMID 36615662, 2022). "Interleukin-9 (IL-9) is a pleiotropic cytokine that acts on a variety of cells and tissues, and plays roles in inflammation and infection as well as tumor immunity." (PMID 35795670, 2022). "Arg1+ macrophages from tumor bearing mice secreted more IL-6 than Arg1- macrophages, and were capable of inducing tumor cell migration in the presence of IL-9." (PMID 35778404, 2022). "In fact, we demonstrated here that anti-IL-9 antibodies given intraperitoneally during tumor development resulted in increased survival rates and enhanced tumor rejection." (PMID 35514957, 2022). "The anti-tumor effect of Th9-derived IL-9 has been well characterized, particularly in subcutaneously injected tumor models." (PMID 35778404, 2022). "Patients with high stromal IL9 expression have a tumor-to-stroma IL9 gradient directed towards the stroma (p=0.019)." (PMID 36131941, 2022). "We next sought to evaluate if IL-9 affected tumor growth and lung macrophages in a primary lung tumor model." (PMID 35778404, 2022). "Down-regulating cholesterol content induces polarization towards Tc9 cells and enhance IL-9 expression and the anti-tumor immunity in vivo." (PMID 36003368, 2022).